MTOR (mechanistic target of rapamycin kinase)
Diseases named in the same sentence as MTOR in open-access papers (continued):
Sharing a sentence is not in itself a finding about the gene and the disease.
prostate carcinoma (continued). "In prostate cancer, the androgen receptor decreases the expression of miR-29b which targets both TET2 and 5-hmC; 5-hmC represses FOXA1 activity, while its reduction activates the mTOR pathway and AR of prostate cancer." (PMID 29850477, 2018). "In summary, our results indicate that Salen-Mn could increase cell autophagy in prostate cancer cells, which may be due to the activation of AMPK and the subsequent inhibition of mTOR activity." (PMID 29156794, 2017). "Compound 37 induced ROS mediated apoptosis in human cervical cancer ME-180 cells, human prostate cancer PC-3 cells and LNCaP cells, G2-M arrest and autophagy by inhibiting the AKT/mammalian target of rapamycin (mTOR) pathway in MCF-7 cells and MDA-MD-231 cells." (PMID 28626426, 2017). "Additionally, ROS play a critical role in salinomycin-induced autophagy regulated via ROS-mediated PI3K/AKT/mTOR and ERK/p38 MAPK pathways in prostate cancer cells." (PMID 28524116, 2017). "Another HIF-1α inhibitor, Bortezomib inhibits p300-HIF-1α binding at nanomolar concentrations (0.6–30 nM), almost equivalent to Compound 12 to repress HIF-1α protein expression and nuclear accumulation by inhibiting both PI3K/Akt/mTOR and MAPK pathways in prostate cancer cells." (PMID 27999195, 2017). "In addition, capsaicin induced in the prostate cancer cell lines PC-3 and LNCaP, an inhibition of the PI3K/Akt/mTOR axe which is generally upregulated in prostate cancer." (PMID 26625315, 2016). "In hormone-insensitive PC-3 and DU145 prostate cancer cells the mTOR inhibitor everolimus (RAD001) alone did not lead to significant cell death, however, it strongly sensitized cells to low levels (5 nM) of docetaxel." (PMID 27821815, 2016). "Immunohistochemical analysis of the evaluable prostate cancer tissue demonstrated submembranous p-mTOR staining in 182 cases (95%), negative staining in 9 cases (5%) or at least 1 core negative in 36 cases (19%)." (PMID 27096957, 2016). "In prostate cancer, CD44 is inhibited by rapamycin via its inhibition of mTOR signaling." (PMID 26202311, 2015). "Furthermore, they showed that levels of phosphorylated mTOR (p-mTOR) and p-S6K increased in the L4-5 dorsal horn and DRG on the side of the prostate cancer cell injection." (PMID 26024835, 2015). "Together, the data demonstrate that blockage of PI3K/mTOR pathway successfully suppress cell proliferation in both AR sensitive and non-sensitive prostate cancer cell lines." (PMID 26506516, 2015). "Expression of miR-99a inhibits the growth of prostate cancer cells and reduces the expression of prostate-specific antigen by targeting chromatin-remodeling factors such as SMARCA5, SMARCD1 and the growth regulator kinase mTOR in vivo." (PMID 24637915, 2014). "As microRNA-99a targets mTOR in prostate cancer cells, the down-regulation of this microRNA in UCB demonstrated in the present study may abolish the tumor-promoting effects of mTOR in the cells, resulting in cancer development." (PMID 25014919, 2014). "Fisetin, a flavonoid, activates AMPK to induce apoptosis in multiple myeloma cells, inhibits PI3K/AKT and mTOR and activates AMPK in non-small cell lung cancer, and induces autophagy-mediated cell death by activating AMPK and suppressing mTOR in prostate cancer cells." (PMID 23875169, 2013). "In addition, we also observed apoptosis of prostate cancer cell by blocking the MAPK/ERK, PI3K/Akt/mTOR, and Hsp90/AR pathways." (PMID 24130883, 2013). "Collectively, PI3K/AKT/mTOR pathway seems to contribute prostate cancer progression not through activation of AR but by facilitating survival of prostate cancer cells upon androgen deprivation." (PMID 23896594, 2013). "Additionally, activation of mTOR pathway, a main downstream effector of the PI3K/AKT pathway, was also reported to have oncogenic functions both in castration-naive and -resistant prostate cancers." (PMID 23896594, 2013).
prostate carcinoma (continued). "Moreover, luteolin reduced cell viability and induced apoptosis in prostate cancer cells, which were correlated with the downregulation of AKT, ERK, mTOR, P70S6K, MMP-2, and MMP-9 expressions." (PMID 23300633, 2012). "Furthermore, quercetin reduced the cell viability and induced apoptosis in prostate cancer cells, which were correlated with the downregulation of AKT, mTOR and P70S6K expressions." (PMID 23094058, 2012). "Taken together, our results suggest that, unlike CSp, SeSp downregulates the Akt/mTOR pathway of prostate cancer LNCaP cells." (PMID 19943972, 2009). "Beyond IGF-1 mediated signaling, prostate cancer progression is strongly supported by activation of the phosphatidylinositol 3-kinase (PI3K), protein kinase B (AKT), and mechanistic target of rapamycin (mTOR) pathway, a major pro-survival axis frequently upregulated in advanced disease." (PMID 41375042, 2025). "Moreover, activation of the AMPK/mTOR signaling pathway with rapamycin inhibited EMT and proliferation by increasing epithelial marker expression (e.g., E-cadherin) and reducing mesenchymal marker expression in prostate cancer cells." (PMID 40661871, 2025). "Similarly, in an independent study, we demonstrated that castration-resistant prostate cancer cells also depend on BRPF1 in docetaxel and cabazitaxel resistance, highlighting BRPF1’s role as an ABCB1 regulator controlling mTOR and unfolded protein response (UPR) signaling." (PMID 40583060, 2025). "According to these results, chitosan salicylaldehyde/CuFe2O4 may have a greater impact than chitosan salicylaldehyde in reducing the expression of PI3K, AKT, mTOR, and Cyclin D1, which in turn prevents the survival and proliferation of PC3 prostate cancer cells." (PMID 39900661, 2025). "Increasing evidence indicates that the PI3K/Akt/mTOR pathway may directly regulate the expression and activation of AR, which necessitates a dual inhibition of both the AR and PI3K/Akt pathways for a durable control of prostate cancer." (PMID 38254705, 2024). "Targeting cell signalling pathways such as the phosphoinositide 3-kinase/mammalian target of rapamycin (PI3K/mTOR) pathway has also been shown to downregulate immunosuppressive cells such as T regulatory cells and may have a role in improving ICI efficacy in prostate cancer." (PMID 37842236, 2023). "More importantly, we found significant differences in several important tumors signaling pathways, mTOR signaling pathway, HIPPO signaling pathway, MAPK signaling pathway, and Ras signaling pathway, which suggests that NSUN2 does have an impact on the development and progression of prostate cancer." (PMID 35978830, 2022). "The FGF-FGFR signaling axis has many downstream effector cascades, including RAS/MAPK, PI3K/AKT/mTOR and JAK/STAT signaling pathways, thus providing potential mechanisms whereby CAF-mediated activation of FGF signaling in prostate cancer cells could promote tumor growth." (PMID 36671452, 2022). "Indeed we discovered that Akt-mTOR-independent mechanisms by GNE-493, including ROS production and oxidative injury, programmed necrosis, SphK1 downregulation, and ceramide accumulation, were also important in mediating prostate cancer cell death." (PMID 35296639, 2022). "Given that our data suggest that PTEN-wt prostate cancer cell lines rely on mGluR1 and HER2 to overcome PI3K/mTOR inhibition, we sought to evaluate whether simultaneous inhibition of both signaling pathways would impact on the tumorigenic potential of these cell lines." (PMID 35086953, 2022). "Indeed, Smad7 regulates expression of HDAC6 in prostate cancer in response to TGF-β53 and HDAC6 may play an indispensable role in balancing the maintenance and activation of primordial follicles through mechanistic target of rapamycin (mTOR) signaling in mice." (PMID 36402791, 2022).
prostate carcinoma (continued). "Overall, light irradiation of prostate cancer cells is shown in the present investigation to profoundly elevate curcumin’s bioavailability, with a concentration of 0.2 μg/mL distinctly blocking tumor proliferation by interacting with the CDK-cyclin axis and the Akt-mTOR pathway." (PMID 34576132, 2021). "Furthermore, mTOR and EGFR co-inhibition with everolimus and gefitinib has shown limited sensitivity in patients owing to enhanced AR activity and PSA levels, providing further rationale for combining AR and PI3K-AKT-mTOR blockade to treat prostate cancer." (PMID 32630372, 2020). "The proportion of prostate cancer patients that could benefit from the PIM-PI3K/mTOR pathway co-targeting is not well-understood or easy to estimate, as a wide range of alterations can result in abnormal pathway activation." (PMID 32873828, 2020). "We determined whether epigenetic modulation by the histone deacetylase (HDAC) inhibitor, valproic acid (VPA), may counteract non-responsiveness to the mTOR inhibitor, temsirolimus, in prostate cancer (PCa) cells." (PMID 31010254, 2019). "Taken together, these data support our hypothesis that the ERK1/2 and AKT pathways may crosstalk through MTOR to control migration and invasion in hypoxic prostate cancer cells lacking Rb." (PMID 28798482, 2017). "Therefore, combined targeting of the PI3K/AKT/mTOR and the Ras/MEK/ERK pathways has been proposed as an alternative approach in a range of different cancers, including multiple myeloma (MM), melanoma and prostate cancer." (PMID 28915623, 2017). "Jointly, these results suggest no clear prostate cancer patient population exists that may benefit from mTOR inhibitor treatment." (PMID 27096957, 2016). "Similarly, although synergistic effect by erlotinib and BKM120 has not been reported, combinations of erlotinib and PI3K/mTOR inhibitors showed synergistic cytotoxicity in cells of prostate cancer, NSCLC and ovarian cancer in previous studies." (PMID 26861698, 2016). "A previous report on mTOR phosphorylation in prostate cancer identified a small subpopulation of p-mTOR negative patients who may benefit from mTOR inhibition by integrating mTOR phosphorylation, ERG fusion and PTEN mutation status." (PMID 27096957, 2016). "Our present study revealed that PrLZ/PC-1 didn't increase IR induced senescence in prostate cancer cells, suggesting PrLZ/PC-1 might did not regulate other mTOR signal downstream targets which were correlated with senescence regulation." (PMID 27694690, 2016). "Previous studies have indicated that the PI3K/Akt/mTOR axis plays important roles in cancer cell proliferation, metabolism, migration, and angiogenesis, and that the inhibition of the AKT signaling pathway can induce apoptosis and prevent the invasion and metastasis of prostate cancer cells." (PMID 25957503, 2015). "Combined targeted inhibition of PI3K/Akt/mTOR, RAS/RAF/MEK, and JAK/STAT signaling may be a promising strategy for the treatment of prostate cancer and PTEN knockout mice should play an important role in the preclinical development and discovery of candidate agents." (PMID 22454635, 2012). "In the prostate cancer mouse models, the majority of TFs perturbed in the Pten null mouse exhibit concordant alterations in their activities when the PTEN downstream AKT/mTOR pathway is manipulated genetically or pharmaceutically by the mTOR inhibitor rapamycin." (PMID 22347425, 2012).
prostate carcinoma (continued). "In the present study, the combined impact of the mammalian target of rapamycin (mTOR)-inhibitor RAD001, the dual EGFr and VGEFr tyrosine kinase inhibitor AEE788 and the histone deacetylase (HDAC)-inhibitor valproic acid (VPA) on prostate cancer growth and adhesion in vitro was investigated." (PMID 21867506, 2011). "The progression of prostate cancer from androgen-dependent to androgen-independent tumors involves the alteration of the androgen receptor and/or the activation of pro-survival pathways, namely those of the Ras/Raf/MEK/ERK and Ras/PI3K/PTEN/Akt/mTOR signaling cascades." (PMID 21422497, 2011). "Therefore, our R26MTA1; Ptenf/f mice mimic a subtype of advanced prostate cancer that exhibits the involvement of mTOR signaling, suggesting that targeting the MTA1/mTOR pathway by natural stilbene gnetin C could be an effective means for blocking prostate cancer progression." (PMID 38611022, 2024). "In earlier studies, using the same large prostate cancer cohort we had described other very strong and often independent prognostic features such as for example ß3-tubulin, CD57, DAXX, HOXB13, KPNA2, RBM3, mTOR, p62, and TYMS, that might also be worth testing in multiparametric prognostic kits." (PMID 28415558, 2017). "Aberrant regulation of two major signalling pathways, mechanistic target of rapamycin (mTOR) and general amino acid control non-depressible 2 (GCN2), is a key driver of reshaping the amino acid metabolism landscape in prostate cancer." (PMID 39859489, 2025). "Although there is an ongoing trail of BEZ235 (a dual PI3K - mTOR inhibitor) in combination with BKM120, no clinical trial of BKM120+TKI258 in prostate cancer is being carried out." (PMID 27783994, 2016). "One study used 3 prostate cancer cell lines (androgen responsive and non-responsive) to develop RR derivates; they identified enhanced EMT/cancer stem cell phenotypes and activation of checkpoint proteins and PI3K/AKT/mTOR signalling pathways in the RR cells." (PMID 30987655, 2019). "Here we show for the first time that in prostate cancer cells mTORC1 increases SK1 expression through HIF-1α in normoxic conditions, a pathway that may be interrupted by mTOR inhibitor RAD001." (PMID 27821815, 2016). "Here we found the Cav-1 mediated increases in VEGF-A secretion to be independent of PI3-K/AKT and mTOR signalling, whereas Cav-1 appears to promote both the production and release of VEGF-A in prostate cancer cells at least in part through the potentiation of PI3-K/AKT signalling." (PMID 24119769, 2013).
glioma (803 papers, 2009 to 2026). A benign or malignant brain and spinal cord tumor that arises from glial cells (astrocytes, oligodendrocytes, ependymal cells). "Concurrently, high-risk gliomas demonstrated hyperactivation of pro-tumorigenic pathways (e.g., mTOR, MAPK) and frequent EGFR amplification." (PMID 41756290, 2026). "Consistently, high mTOR activity in Grade 4 gliomas has been linked to elevated activity of the cystine–glutamate antiporter xCT, which facilitates glutamate secretion and couples metabolic state to excitatory output." (PMID 40705199, 2025). "In glioma stem cells, overactivation of mTOR is often associated with abnormal cell proliferation and survival." (PMID 39944825, 2025). "Aberrant mTOR activation is a hallmark of gliomas and is driven by upstream alterations such as EGFR amplification, PTEN loss, and PI3K mutations, all converging to increase signaling through the PI3K-Akt-mTOR pathway." (PMID 41301687, 2025). "For instance, the phosphatidylinositol 3‐kinase (PI3K)/Akt/rapamycin‐sensitive mTOR‐complex (mTOR) pathway is one of the key signaling pathways activated and affected in gliomas, and associated mutations can be found in most GB patients." (PMID 40277152, 2025). "The exact mechanism by which mTOR signaling contributes to epileptogenesis is yet to be elucidated (see “Glioma-associated epilepsy and mTOR pathway alterations”)." (PMID 41074169, 2025). "One study showed that L. lucidum extract inhibited glioma tumor growth in vivo and induced glioma cell death in vitro, the underlying mechanism involved in the regulation of the Akt/mammalian target of rapamycin (mTOR)/survivin pathway." (PMID 38933667, 2024). "MHC-linked Th1 response through the mTOR pathway was activated only for a few time steps in the glioma scenario." (PMID 38481985, 2024). "Further, the Akt/mTOR signaling pathway has been implicated in maintaining the stem cell properties of CSCs in glioma." (PMID 38474373, 2024). "According to metabolomics research, the PI3K/AKT/mTOR pathway is associated with the development of glioma‐related epileptogenesis." (PMID 38641945, 2024). "Knockdown of PHLDA2 activated apoptosis and autophagy, eventually causing inhibition of tumor growth through AKT/mTOR signaling in both colorectal cancer and glioma." (PMID 39033192, 2024). "This study aims to determine and correlate the expression of autophagy markers, autophagy-associated signaling genes (PI3K/Akt/mTOR), and autophagy-associated miRs in both low and high-grade glioma." (PMID 39348350, 2024). "IDH119 mutations activated the mTOR signalling pathway, promoting the proliferation and invasion of glioma cells." (PMID 39620895, 2024). "As already mentioned, high AKT levels and mTOR activation are associated with an inhibition of autophagy initiation and are strongly associated with high-grade gliomas compared to low-grade tumours." (PMID 37174088, 2023). "Another important observation is that miRNAs cause inhibition of the mTOR pathway in gliomas, leading to attenuation of glioma cell migration and invasion." (PMID 38275375, 2023). "Liposomes inhibited the Akt/mTOR signaling pathway by regulating glucose metabolism and causing death by autophagosome formation in C6 glioma." (PMID 37273792, 2023). "Gαi1, along with Gαi3, associated with RTKs in human glioma tissues, essential for the downstream Akt-mTOR activation." (PMID 38049415, 2023). "Previously, it has been reported that increased oxidative stress and reduced proliferation via inactivation of PI3K/AKT/mTOR pathway is often linked to the induction of apoptosis in glioma." (PMID 37025487, 2023). "The PI3K/Akt/mTOR signaling pathway is one of the key pathways in tumor progression, and its molecular alteration is a typical hallmark of glioma." (PMID 36856182, 2023). "Activation of the mTOR pathway within glioma-associated microglia is about twice as high as in peripheral tissues." (PMID 37700840, 2023).